CD47 (CD47 molecule)
Diseases named in the same sentence as CD47 in open-access papers (continued):
Sharing a sentence is not in itself a finding about the gene and the disease.
lung cancer (continued). "Our previous work found that CD47 blockade enhanced macrophage phagocytosis of tumor cells both in vivo and in vitro, enhancing the therapeutic effect of cisplatin on lung cancer in vitro and in vivo." (PMID 36054073, 2022). "In this study, we designed the structure CD47scFv-hinge-CD4TM-CD28-41BB-CD3ζ to create CAR-T cells to destroy CD47+cancer cells, more specifically, lung cancer cell line A549." (PMID 34189144, 2021). "For example, CDDP treatment in lung cancer cells was shown to induce CD47 expression, leading to a reduction in the phagocytic activity of co-cultured macrophages, while the CD47 blockade enhanced the cytotoxic effect of CDDP." (PMID 34576193, 2021). "Similar to what has been observed in lung cancer, CD47 positively correlates with SLFN11 expression in prostate carcinoma but not in normal prostate tissue." (PMID 34571887, 2021). "To further reveal the role of CD47 in H2-mediated lung cancer inhibition, we also performed the gain-of-function assay." (PMID 32314789, 2020). "CD47 is overexpressed in various cancers, such as acute lymphocytic leukaemia, myeloma, non-Hodgkin’s lymphoma and lung cancer." (PMID 33014356, 2020). "With the aim of further exploration of the mechanism of H2 in suppressing lung cancer progression, the present study illustrates that H2 represses the progression of lung cancer via down-regulating CD47." (PMID 32314789, 2020). "In the current study, we aimed to elucidate the roles of CD47 in H2-mediated inhibition of lung cancer progression though carrying out both in vivo and in vitro experiments." (PMID 32314789, 2020). "In conclusion, the present study makes clear that H2 exerts an anti-tumor role in lung cancer via down-regulating CD47, an antiphagocytic molecule." (PMID 32314789, 2020). "In A549 and NCI-H520 lung cancer cells that ectopically express CD47, decreasing Cdc42 levels reduced cancer cell migration and invasion." (PMID 32082311, 2020). "CD47 protein and mRNA levels are also overexpressed on the surfaces of lung cancer cells, and by SCLC tumors and non-small cell lung cancer (NSCLC) tumors." (PMID 32082311, 2020). "Up-regulation of CD47 abolished H2 roles in promoting lung cancer cell apoptosis and repressing cell growth, invasion and migration in both A549 and H1975 cell lines." (PMID 32314789, 2020). "In support of this strategy, the administration of CD47-specific mAb inhibited in vivo the growth of xenografted tumors developed from patient-derived lung cancer cells or cancer stem cells by recruiting macrophages into the tumor microenvironment." (PMID 32082304, 2019). "We first tested the ability of anti-human CD47 antibody to enable phagocytosis of human lung cancer cell lines and primary lung cancer cells by human and mouse macrophages in vitro." (PMID 28484448, 2017). "We have also indicated that anti-CD47-blocking antibody is effective for treating human lung cancer and CSCs in vitro and in vivo." (PMID 28484448, 2017). "This study was to explore if the expression of CD47 is the mechanism used by lung cancer cells, especially CSCs, to escape phagocytosis in vitro and in vivo." (PMID 28484448, 2017). "Disruption of the CD47–SIRPα interaction with anti-human or anti-mouse SIRPα antibody also resulted in significant phagocytosis of lung cancer cells." (PMID 28484448, 2017). "Here, we also detected the efficacy of anti-CD47 antibody to inhibit lung cancer cell growth as a monotherapy." (PMID 28484448, 2017). "We show that CD47 is highly expressed on lung cancer cells and lung CSCs compared to its normal counterparts." (PMID 28484448, 2017). "We have validated an important function of CD47 on lung cancer cells, especially lung CSCs, as a “don’t-eat-me” signal." (PMID 28484448, 2017). "Blocking antibodies that dismiss the interaction between CD47 and SIRPα enable the phagocytosis of lung cancer cells and CSCs in vitro and inhibited tumor growth in several xenotransplantation models." (PMID 28484448, 2017).
lung cancer (continued). "In these two additional xenotransplantation models, anti-CD47 antibody treatment eliminated all of the primary lung cancer cells and primary lung CSCs in mice and significantly prolonged survival compared to IgG control." (PMID 28484448, 2017). "Blocking CD47 function with anti-CD47 antibodies enabled macrophage phagocytosis of lung cancer cells and lung CSCs." (PMID 28484448, 2017). "In our study, anti-human CD47 antibody remarkably enhanced the phagocytosis of lung cancer cell lines and primary tumor cells in vitro and significantly inhibited tumor growth in lung cancer cell and primary tumor cell xenotransplantation models." (PMID 28484448, 2017). "Anti-CD47 antibodies inhibited tumor growth in immunodeficient mouse xenotransplantation models established with lung cancer cells or lung CSCs and improved survival in tumor-bearing animals." (PMID 28484448, 2017). "Across different lung cancer subtypes, we found varying levels of CD47 expression that was significantly different within each lung cancer subtype." (PMID 28484448, 2017). "Next, we detected the ability of anti-CD47-blocking antibody to eliminate lung cancer cells and lung CSCs in vivo by two different treatment strategies." (PMID 28484448, 2017). "First, the effect of ex vivo anti-CD47 antibody coating on the engraftment of human lung cancer cells and lung CSCs was tested." (PMID 28484448, 2017). "In this study, we indicate that higher expression of CD47 is also the mechanism used by lung cancer cells, especially lung CSCs, to escape phagocytosis." (PMID 28484448, 2017). "In the second treatment strategy, mice were first engrafted with lung cancer cells or lung CSCs and then administered anti-CD47 B6H12.2 antibody therapy." (PMID 28484448, 2017). "In conclusion, we found that CD47 is expressed on lung cancer cells and lung CSCs, and CD47 and CD133 levels as prognostic factors can be useful in risk-adapted therapy decision-making of lung cancer patients." (PMID 28484448, 2017). "The CD47:SIRPα interaction is involved in the pathogenesis of lung cancer and other cancer types when tumors release cytokines promoting tumor growth and stimulating the conversion of macrophages from M1 to M2 phenotype." (PMID 26941482, 2016). "In lung cancer and in several types of cancers including breast, bladder, colon, pancreatic, and hematological cancers, blocking CD47 in tumor cells leads to increased phagocytosis by macrophages and later activation of T cells." (PMID 26941482, 2016). "We observed a positive correlation between STAT3 and CD47 expression in lung cancer." (PMID 41438583, 2026). "Elevated soluble CD47 in the serum of lung cancer patients further supports immune evasion." (PMID 40739089, 2025). "Confocal analysis further confirmed that TRAF2 co‐localized with CD47 in lung cancer cells." (PMID 39665172, 2025). "We next determined if CD47 could exert a functional role to protect lung cancer cells from macrophage phagocytosis and whether treatment with EGFR TKIs could enhance phagocytosis." (PMID 38483480, 2024). "Together, these findings suggest expression of these molecules may vary based on the driver mutation, but both CD47 and MHC class I molecules may be important macrophage immune checkpoints for lung cancers with driver mutations." (PMID 38483480, 2024). "Our findings provide the first evidence, to our knowledge, that KRAS mutations could suppress the innate antitumor immune response by regulating CD47 expression in lung cancer cells." (PMID 36413402, 2023). "CD47 is required for a KRAS-driven antiphagocytic effect in lung cancer." (PMID 36413402, 2023). "The first report demonstrating that disrupting the CD47–SIRPα interaction in lung cancer had anti-tumor effects was that by Weiskopf and colleagues, who showed that CD47 blockade with a mAb in SCLC cell lines and patient-derived xenografts enhanced cancer cell phagocytosis by macrophages." (PMID 37958404, 2023).
lung cancer (continued). "This review summarizes the roles of CD47 in tumor biology, its therapeutic potential in non-small cell lung cancer, and challenges that must be overcome to facilitate the clinical translation of CD47-targeted immunotherapy to improve lung cancer survival rates." (PMID 37958404, 2023). "Next, we evaluated the effect of miR-34a on the antiphagocytic activity of CD47 in lung cancer." (PMID 36413402, 2023). "In addition to oncogenes and cytokines, multiple groups have shown that standard of care lung cancer therapies upregulate CD47 expression." (PMID 37958404, 2023). "Taken together, this evidence suggests that multiple lung cancer therapies could upregulate CD47 through a JAK–STAT–IFN pathway." (PMID 37958404, 2023). "Targeting the CD47-SIRPα checkpoint is also a potential strategy for lung cancer immunotherapy." (PMID 36823443, 2023). "Furthermore, because CD47 and PD‐L1 were overexpressed in lung carcinoma tissue, the images of immunofluorescence sections of tumor tissue indicated that the aCD47 and aPD‐L1 antibodies were bonded to their antigens." (PMID 37132609, 2023). "As a therapeutic target, anti-CD47 antibody has shown promising results in diffuse large B-cell lymphoma, pediatric malignant brain tumor, ovarian cancer, hepatocellular carcinoma, and lung cancer." (PMID 36291980, 2022). "95D is a highly metastatic lung cancer cell line with high expression of CD47 glycoprotein." (PMID 35646646, 2022). "Huyen designed a third generation of CD47-CAR-T cell that could effectively kill lung cancer cells (A549) and inhibit lung cancer cell metastasis." (PMID 35418166, 2022). "Cell surface expression of CD47 on different lung cancer cell lines." (PMID 35646646, 2022). "H2 treatment inhibited CD47 expression and induced apoptosis of A549 lung cancer cells." (PMID 33482814, 2021). "High expression of CD47 is found in nonsmall cell lung cancer, and these cancers could easily escape the immune system." (PMID 34189144, 2021). "To conclude, the future design of novel lung cancer therapies should consider polarization of macrophage to M1 phenotype through exogenous upregulation of miR-155 or miR-1207-5p, suppression of miR-21, or miR-103a, inhibition of IL-10 and agonist of CD47." (PMID 32477352, 2020). "Here, we revealed that H2 treatment could negatively modulate CD47 expression, which might be the mechanism by which H2 inhibited lung cancer progression." (PMID 32314789, 2020). "Using sequencing technique, we found that H2 induced a significant reduction in CD47 expression in lung cancer A549 cells, but weather CD47 is involved in H2-mediated inhibition in lung cancer progression still remains unclear." (PMID 32314789, 2020). "Our research group previously revealed that H2 treatment could induce a significant decrease in CD47 expression, indicating that CD47 might be involved in H2-mediated lung cancer inhibition." (PMID 32314789, 2020). "Therefore, the present study aimed to explore the effects of CD47 on H2-induced lung cancer repression." (PMID 32314789, 2020). "CD47 overexpression correlated with tumor progression and shorter survival in lung cancer." (PMID 32043750, 2020). "In our previous study, our project group found that H2 could decrease the expression of CD47 in lung cancer A549 cells via the next-generation sequencing, indicating that CD47 might be involved in H2-mediated lung cancer repression." (PMID 32314789, 2020). "In conclusion, the current study reveals that H2 inhibits the progression of lung cancer via down-regulating CD47, which might be a potent method for lung cancer treatment." (PMID 32314789, 2020). "This study was to explore whether the expression of CD47 is the mechanism used by lung cancer cells, especially CSCs, to escape phagocytosis in vitro and in vivo." (PMID 28484448, 2017). "In contrast, human and mouse macrophages could efficiently phagocytose lung cancer cells treatment with the anti-human CD47-blocking antibody B6H12.2." (PMID 28484448, 2017).
lung cancer (continued). "Monoclonal antibodies targeting CD47 enabled the phagocytosis of patient-derived lung cancer cells and CSCs in vitro and inhibited the in vivo growth of xenografted tumors developed from patient-derived lung cancer cells or CSCs." (PMID 28484448, 2017). "We further detected whether the anti-human CD47 antibody can influence the apoptosis or proliferation of lung cancer cells or lung CSCs." (PMID 28484448, 2017). "To determine whether CD47 mRNA level serves as a prognostic factor in human lung cancers, we retrospectively analyzed gene expression data of 317 lung cancer patients including 100 AC, 147 SCC, and 70 SCLC." (PMID 28484448, 2017). "Recent studies show the importance of CD47 in the interaction with macrophages inhibiting phagocytosis and promoting the migration of neutrophils, increasing inflammation which can lead to recurrence and progression in lung cancer." (PMID 26941482, 2016). "Moreover, CD47 loss-of-function significantly diminished the ability of NSCLC cells to metastasize in vivo, demonstrating the physiological relevance of cell-intrinsic CD47 signaling in lung cancer cells." (PMID 42007973, 2026). "The following Boolean search string was applied: (“lung cancer” OR “pulmonary neoplasm” OR “NSCLC”) AND (“SPIONs” OR “superparamagnetic iron-oxide nanoparticle” OR “magnetic nanoparticle”) AND (“biomimetic” OR “cell membrane” OR “camouflage” OR “CD47” OR “integrin αvβ3”)." (PMID 41155938, 2025). "Finally, we review the literature supporting CD47 as a promising immunotherapeutic target in lung cancer and offer our perspective on key obstacles that must be overcome to establish CD47 blockade as the next standard of care for lung cancer therapy." (PMID 37958404, 2023). "Additional studies are needed to determine (i) whether phagocytosis induced by CD47 blockade in lung cancer is differentially executed by M1 versus M2 macrophages as previously suggested, and (ii) whether immune-independent effects of CD47 inhibition also contribute to its anti-tumor efficacy." (PMID 37958404, 2023). "In addition, CD47 expression was observed to be elevated in CD133+ lung cancer cells." (PMID 35740975, 2022). "Hence, CD47 expression may be another mechanism used by lung cancer cells, especially lung CSCs, to escape phagocytosis." (PMID 32244422, 2020). "However, knockdown of CD47 enhanced H2 role in lung cancer inhibition." (PMID 32314789, 2020). "In addition, the identification of CD47 and CD133 levels as prognostic factors could be incorporated into standard clinical prognostic considerations across multiple subtypes of lung cancer and may be useful in risk-adapted therapy decision-making." (PMID 28484448, 2017). "To determine whether this was true, we screened several CSC markers: CD117 and CD133 are identified as CSC markers of lung cancer, CD87 is associated with a CSC-like property in SCLC, and CD47 is highly expressed on virtually all human solid tumors, including lung cancer." (PMID 29312632, 2017). "However, it is unclear how CD47 is involved in lung cancer initiation and progression." (PMID 28484448, 2017). "Thus, CD47 activation appears to be tightly correlated with cell migration and invasion ability; hence, CD47 might be an important regulator of migration and invasion in lung cancer cells." (PMID 27411490, 2016). "The results showed that GMI enhanced macrophage phagocytosis of lung cancer cells by inhibiting STAT3 and reducing CD47 expression." (PMID 41438583, 2026). "Overexpressed STAT3 restored GMI-induced apoptosis and GMI-reduced transcription of CD47 in HCC827 and H1975 lung cancer cells." (PMID 41438583, 2026). "We aimed to cross-validate these findings on human and murine lung cancer cells and observed that CD133 + CSC differentially expressed higher levels of HA, HAS3, ABCC5, SOX2, and CD47 (p < 0.01)." (PMID 39039104, 2024).
lung cancer (continued). "We also tested a patient-derived xenograft model of EGFR mutant lung cancer (MGH134-1) and again observed the greatest antitumor effects from the combination treatment of osimertinib with an anti-CD47 antibody." (PMID 38483480, 2024). "CD47 was the top-ranked gene co-expressed with IFT57 in breast, bladder, ovarian, endometrial, thyroid, and lung carcinomas." (PMID 39201643, 2024). "Since then, several transcriptomic and proteomic studies have demonstrated CD47 expression in SCLC, LUAD, and LUSC tumors and CD133+ lung cancer stem cells." (PMID 37958404, 2023). "Our findings are in line with a previous study on non‐small cell lung cancer (NSCLC), investigating both human tumor tissues and cancer cell lines, indicating that high expression of CD47 and CD68 promotes tumor invasion and metastasis." (PMID 36598153, 2023). "In clinical studies, CD47 expression has been reported to be upregulated in CSCs of HCC, pancreatic ductal adenocarcinoma, and lung cancer." (PMID 35740975, 2022). "Here we combine radiotherapy with blockade of the ‘don’t-eat-me’ cell-surface molecule CD47 in small cell lung cancer (SCLC), a highly metastatic form of lung cancer." (PMID 36411318, 2022). "As expected, at the protein expression level, we found that the expression of CD47 and CD24 in lung tissue of lung cancer mice was significantly increased compared with healthy mice." (PMID 36186906, 2022). "How about the effect of IL-6 antibody combination with CD47 and PD-L1 ICIs in patients with IPF or lung cancer combined with IPF?" (PMID 36544757, 2022). "We also detected enhanced CD47 levels in SARS-CoV-2-infected primary human bronchial epithelial cells (HBE) grown in air−liquid interface (ALI) cultures and Calu-3 lung cancer cells." (PMID 34698067, 2021). "Cdc42 expression level is positively correlated with CD47 expression level in A549 and NCI-H520 lung cancer cell lines." (PMID 32082311, 2020). "Increased CD47 and CD133 expression levels in lung cancer patients correlated with a decreased probability of survival." (PMID 28484448, 2017). "We further analyzed the expression correlation of CD47 and CD133 mRNA in the 317 lung cancer patients." (PMID 28484448, 2017). "The mRNA expression levels of CD47 and CD133 correlated with a decreased probability of survival for multiple types of lung cancer." (PMID 28484448, 2017). "For example, EGFR mutant lung cancers may express higher levels of MHC I molecules, while KRAS mutant cancers may express lower levels of CD47 and MHC I molecules." (PMID 38483480, 2024). "Notably, treatment of lung cancer cells with the EGFR tyrosine kinase inhibitor, gefitinib, or the KRAS-G12C inhibitor, AMG 510, reduced CD47 expression, which is consistent with the newly discovered mechanisms of CD47 regulation by EGFR and KRAS." (PMID 37958404, 2023). "In samples of lung adenocarcinoma from patients and Kras-driven genetic mouse models of lung cancer, mutant KRAS activated the expression of cluster of differentiation 47 (CD47), an antiphagocytic signal in cancer cells, leading to decreased phagocytosis of cancer cells by macrophages." (PMID 36413402, 2023). "Although these percentages are variable, they consistently indicate that CD47 expression is a recurrent feature in lung cancer regardless of subtype." (PMID 37958404, 2023). "Overexpression of CD47 mRNA in lung cancer relative to non-malignant tissues was first discovered in SCLC cell lines and patient-derived xenografts." (PMID 37958404, 2023). "Moreover, we used 2 human lung cancer cell lines, H358 (KRASG12C) and SK-LU-1 (KRASG12D), to further illustrate the potential regulation of CD47 by KRAS." (PMID 36413402, 2023). "Weiskopf and colleagues later confirmed that CD47 was upregulated in SCLC and reported CD47 to be a promising immunotherapeutic target, which stimulated numerous investigations into CD47′s clinical significance in lung cancer." (PMID 37958404, 2023).